SMN1 (survival of motor neuron 1, telomeric)
Diseases named in the same sentence as SMN1 in open-access papers (continued):
Sharing a sentence is not in itself a finding about the gene and the disease.
spinal muscular atrophy (continued). "Spinal muscular atrophy arises from mutations in the survival motor neuron 1 (SMN1) gene, which often leads to the deficiency of the ubiquitous SMN protein." (PMID 29850487, 2018). "For example, in spinal muscular atrophy, causative loss-of-function mutations in SMN1 can be rescued by a recently approved therapy which uses an antisense compound to promote exon retention in an alternatively spliced yet otherwise identical paralog, SMN2." (PMID 30216339, 2018). "Spinal muscular atrophy (SMA) is caused by deletions or mutations of Survival Motor Neuron 1 (SMN1) gene." (PMID 28775379, 2017). "Spinal muscular atrophy (SMA) is a devastating motor neuron disease caused by mutations of the survival motor neuron 1 (SMN1) gene." (PMID 28159932, 2017). "It has been linked to spinal muscular atrophy in humans through its interaction with SMN1, and is one of six genes deleted in a human developmental microdeletion syndrome." (PMID 28936620, 2017). "Spinal muscular atrophy (SMA) is caused by homozygous mutation of the survival motor neuron 1 (SMN1) gene." (PMID 29066780, 2017). "Spinal muscular atrophy is due to mutations affecting the SMN1 gene coding for the full-length protein (survival motor neuron; SMN) and the SMN2 gene that preferentially generates an exon 7-deleted protein (SMNΔ7) by alternative splicing." (PMID 29292768, 2017). "Spinal muscular atrophy (SMA) is a neurodegenerative disease caused by mutation of the survival of motor neuron 1 (SMN1) gene." (PMID 28811488, 2017). "Mutation/deletion of SMN-coding gene, SMN1, accounts for 95% of spinal muscular atrophy (SMA), an autosomal recessive disorder that results in degeneration of α-motor neurons in the spinal cord." (PMID 28101374, 2017). "Spinal muscular atrophy (SMA) is an inherited neuromuscular disease resulting from a recessive mutation in the SMN1 gene." (PMID 27331400, 2016). "Deletion of and/or mutations in SMN1 coupled with the inability of SMN2 to compensate for the loss of SMN1 leads to spinal muscular atrophy (SMA), a leading genetic disease of children and infants." (PMID 27111068, 2016). "For instance, the loss of survival motor neuron protein 1 (SMN1) function affects biogenesis of small nuclear RNA (snRNA) and lead to widespread splicing changes in spinal muscular atrophy (SMA)." (PMID 27352031, 2016). "Spinal muscular atrophy (SMA) is caused by defects in the survival motor neuron 1 (SMN1) gene that encodes survival motor neuron (SMN) protein." (PMID 26953792, 2016). "Spinal Muscular Atrophy (SMA) is caused by mutation or deletion of the survival motor neuron 1 (SMN1) gene." (PMID 27698380, 2016). "Spinal muscular atrophy (SMA) is an autosomal recessive motor neuron disorder caused by mutations in the survival of motor neuron 1 (SMN1) telomeric gene, resulting in a reduced amount of functional full-length SMN protein." (PMID 27769560, 2016). "E7 skipping in SMN1 leads to spinal muscular atrophy (SMA), and SNPs that cause this aberrant skipping have been identified in patients at the downstream 5′SS7 at the +6 site (+6T → G)." (PMID 26833277, 2016). "Both survival of motor neuron (SMN) genes are associated with spinal muscular atrophy; mutations in SMN1 cause the disease, and SMN2 modulates its severity." (PMID 27917293, 2016). "Spinal muscular atrophy is a childhood motor neuron disease caused by mutations or deletions in the SMN1 gene." (PMID 26374403, 2015). "For example, spinal muscular atrophy is caused by deletions or mutations in the gene that encodes survival of motor neuron 1 (SMN1) and the SMN1 protein is ubiquitously expressed and plays a critical role in assembly of the spliceosome and mRNA processing." (PMID 25885816, 2015). "Spinal muscular atrophy (SMA) is an inherited neuromuscular disease caused by deletion or mutation of SMN1 gene." (PMID 25781985, 2015). "Spinal muscular atrophy (SMA) is a neuromuscular disorder caused by mutations of the survival of motor neuron 1 (SMN1) gene." (PMID 25801509, 2015).
spinal muscular atrophy (continued). "Spinal muscular atrophy (SMA) is a neuromuscular disease caused by mutations in Survival Motor Neuron 1 (SMN1), leading to degeneration of alpha motor neurons (MNs) but also affecting other cell types." (PMID 26114395, 2015). "Spinal muscular atrophy (SMA) is caused by SMN1 dysfunction, and the copy number of SMN2 and NAIP can modify the phenotype of SMA." (PMID 25888055, 2015). "Gems contain the survival motor neuron (SMN) protein encoded by the SMN1 gene, which is frequently mutated or deleted in spinal muscular atrophy." (PMID 29124132, 2015). "Spinal muscular atrophy is caused by a functional deletion of SMN1 on Chromosome 5, which leads to a progressive loss of motor function in affected patients." (PMID 26468953, 2015). "Proximal spinal muscular atrophy (SMA) is an autosomal recessive neuromuscular disorder caused by the homozygous deletion or mutation of the survival of motor neuron 1 (SMN1) gene, resulting in a deficiency of the ubiquitously expressed SMN protein." (PMID 25801509, 2015). "Spinal muscular atrophy (SMA) is a human genetic disease which occurs because of the deletion or mutation of SMN1 gene." (PMID 24616638, 2014). "Mutations in the survival motor neuron (SMN1) gene lead to the neuromuscular disease spinal muscular atrophy (SMA)." (PMID 24691550, 2014). "The plastin 3 (PLS3) gene acts as a modifier of the clinical penetrance of autosomal recessive spinal muscular atrophy, caused by the homozygous deletion of the SMN1 gene." (PMID 23820649, 2013). "Spinal muscular atrophy (SMA) is an inherited neurodegenerative disease caused by homozygous inactivation of the SMN1 gene and reduced levels of the survival motor neuron (SMN) protein." (PMID 23967270, 2013). "The childhood neuromuscular disease spinal muscular atrophy (SMA) is caused by mutations or deletions of the survival motor neuron (SMN1) gene." (PMID 24119341, 2013). "Loss-of-function mutations in SMN1 cause spinal muscular atrophy (SMA), a leading genetic cause of infant mortality." (PMID 24014320, 2013). "SMN1 deficiency in lymphoblasts from patients with spinal muscular atrophy led to splicing defects in U12-type introns from the ATXN10 gene." (PMID 23752268, 2013). "Loss of the survival motor neuron gene (SMN1) is responsible for spinal muscular atrophy (SMA), the most common inherited cause of infant mortality." (PMID 24324819, 2013). "Spinal muscular atrophy (SMA) is a neuromuscular disease resulting from mutations in the survival motor neuron 1 (SMN1) gene." (PMID 24134804, 2013). "Exclusion of the exon 7 of SMN2 gene, combined with the primary deletion of SMN1 gene, is the cause of the spinal muscular atrophy (SMA)." (PMID 24069033, 2013). "Spinal muscular atrophy (SMA) is a lethal autosomal recessive disease caused by a genetic defect in the SMN1 (survival motor neuron) gene." (PMID 25562650, 2013). "Functional deficiency of SMN1 is the molecular cause of spinal muscular atrophy (SMA) (OMIM 253300, OMIM 253550, OMIM 253400 and OMIM 271150), a degenerative disorder of spinal cord motor neurons." (PMID 24040563, 2013). "The universal presence of a gene (SMN2) nearly identical to the mutated SMN1 gene responsible for Spinal Muscular Atrophy (SMA) has proved an enticing incentive to therapeutics development." (PMID 22558076, 2012). "Spinal Muscular Atrophy (SMA) is a neurodegenerative motor neuron disorder resulting from a homozygous mutation of the survival of motor neuron 1 (SMN1) gene." (PMID 22558154, 2012). "The inability of SMN2 to compensate for the loss of SMN1 results in spinal muscular atrophy (SMA), a leading genetic cause of infant mortality." (PMID 23185376, 2012). "It is thought that this gene is a modifier of spinal muscular atrophy caused by mutations in a neighbouring SMN1 gene." (PMID 22545106, 2012).
spinal muscular atrophy (continued). "Deletion or mutation(s) of the survival motor neuron 1 (SMN1) gene causes spinal muscular atrophy (SMA), a neuromuscular disease characterized by spinal motor neuron death and muscle paralysis." (PMID 21385431, 2011). "Further investigation revealed that he is heterozygous for a duplication of a thymine nucleoside in his SMN1 gene at position 91 in codon 31, which causes a frame shift mutation and is consistent with spinal muscular atrophy." (PMID 21605440, 2011). "Spinal muscular atrophy is a severe neurogenic disease that is caused by mutations in the human survival motor neuron 1 (SMN1) gene." (PMID 21490958, 2011). "Mutations in human SMN1 are known to cause spinal muscular atrophy (SMA), the most common genetic cause of early lethality in children and abnormal variants have been implicated in sporadic ALS." (PMID 20946666, 2010). "Spinal muscular atrophy (SMA) is an autosomal recessive neuromuscular disorder caused by homozygous mutations of the SMN1 gene." (PMID 21339974, 2010). "Reduced levels of SMN due to mutations or deletions of the SMN1 gene cause the common neurodegenerative disorder spinal muscular atrophy (SMA), the leading genetic cause of infant mortality worldwide, which affects approximately one in 6,000 infants." (PMID 21072240, 2010). "Deletion or mutation(s) of the survival motor neuron 1 (SMN1) gene causes spinal muscular atrophy (SMA)." (PMID 19445707, 2009). "Spinal muscular atrophy (SMA) is an autosomal recessive hereditary disorder caused by mutations of the survival motor neuron 1 (SMN1) gene." (PMID 19480685, 2009). "Spinal Muscular Atrophy is a neurodegenerative disease that is caused by mutations or deletions in the survival of motor neuron 1 (SMN1) gene." (PMID 19997596, 2009). "Spinal muscular atrophy (SMA) is caused by mutations in the Survival Motor Neuron 1 (SMN1) gene." (PMID 39976226, 2025). "Over the past few years, base editing has been successfully applied in mouse models to address various genetic diseases; for example, spinal muscular atrophy is caused by mutations in the gene SMN1, resulting in a deficiency of the SMN protein essential for the survival of motor neurons." (PMID 40745001, 2025). "Spinal Muscular Atrophy (SMA) is caused by mutations in the SMN1 gene." (PMID 39937575, 2025). "Spinal muscular atrophy (SMA) is a motor neuron disease caused by mutations in the SMN1 gene." (PMID 39829133, 2025). "Spinal muscular atrophy (SMA) is a rare autosomal recessive neuromuscular disorder caused by biallelic mutations in the SMN1 gene, leading to a deficiency of survival motor neuron (SMN) protein and progressive degeneration of anterior horn cells in the spinal cord." (PMID 40566025, 2025). "Among the 415 women screened for spinal muscular atrophy—SMN1 gene carrier, 13 patients (3.1%) with SMN1 gene carrier were detected, including 11 males and 2 carriers, i.e., two parents carried the SMN1 pathogenic mutation gene concurrently, and the detection rate was 0.5%." (PMID 38562051, 2024). "5q spinal muscular atrophy (SMA) is an autosomal-recessive motor neuron disease caused by the bi-allelic loss of function of the survival of motor neuron 1 (SMN1) gene on chromosome 5q13 with at least one functional copy of the paralogous survival of motor neuron 2 (SMN2) gene." (PMID 39596191, 2024). "Spinal muscular atrophy (SMA) is a rare but severe neurogenetic disorder primarily caused by loss of or mutation in the survival motor neuron 1 (SMN1) gene on chromosome 5q13, which leads to degeneration of α-motor neurons with resulting muscular atrophy and impairment of motor neuron function." (PMID 39736792, 2024). "Spinal muscular atrophy (SMA) is a neurodegenerative disorder caused by mutations in SMN1 that determine a reduction in SMN protein and a resulting loss of alpha motor neurons (MNs) in the brainstem and spinal cord, followed by progressive muscle weakness and atrophy, as well as early death." (PMID 37238925, 2023).
spinal muscular atrophy (continued). "Spinal muscular atrophy (SMA) is an autosomal recessive neuromuscular disorder caused by reduced levels of survival of motor neuron (SMN) protein due to homozygous deletions or loss-of-function mutations in the SMN1 gene." (PMID 36735057, 2023). "Spinal muscular atrophy (SMA) is a rare autosomal-recessive neurodegenerative disorder caused by mutations in survival motor neuron 1 (SMN1) gene, and consequent loss of function of SMN protein, which results in progressive loss of lower motor neurons, and muscular wasting." (PMID 37705059, 2023). "We used the spinal muscular atrophy genetic model with SMN protein deficiency due to SMN1 mutation." (PMID 36817727, 2023). "Spinal muscular atrophy (SMA) is a neuromuscular disease resulting from mutations or deletions in SMN1 that lead to progressive death of alpha motor neurons, ultimately leading to severe muscle weakness and atrophy, as well as premature death in the absence of treatment." (PMID 37238925, 2023). "Spinal Muscular Atrophy (SMA) is a neuromuscular disease characterized by the degeneration of motor neurons in the anterior horn of the spinal cord caused by mutations in the survival of motor neuron 1 gene (SMN1)." (PMID 38091267, 2023). "Spinal muscular atrophy (SMA) is an autosomal recessive neuromuscular disease caused by deficiency of survival motor neuron (SMN) protein resulting from biallelic deletions or pathogenic variants of the SMN1 (survival motor neuron 1) gene." (PMID 35715567, 2022). "Spinal muscular atrophy (SMA) is caused by survival motor neuron 1 SMN1 deletion." (PMID 35456491, 2022). "Spinal muscular atrophy (SMA) is caused by SMN1 gene mutations leading to lowered SMN expression." (PMID 33823304, 2022). "Further, SOD1, C9orf72, and SMN1 have been identified as causative genes for amyotrophic lateral sclerosis and spinal muscular atrophy, in which the viability of spinal motor neurons is decreased, and treatment strategies targeting these genes are under development." (PMID 35743104, 2022). "Spinal muscular atrophy is associated with mutations of the SMN1 gene." (PMID 36504644, 2022). "Spinal muscular atrophy (SMA) is caused by homozygous deletions or mutations in the survival motor neuron 1 (SMN1) gene, resulting in reduced expression of the SMN protein, which leads to the progressive degeneration of motor neurons and atrophy of skeletal muscle." (PMID 36291640, 2022). "The survival motor neuron 1 (SMN1) gene is mutated in spinal muscular atrophy (SMA)." (PMID 35745855, 2022). "Spinal muscular atrophy (SMA) is a genetic disorder caused by genetic defect of SMN1 gene." (PMID 33429824, 2021). "5q-Spinal muscular atrophy (SMA) is an autosomal-recessive inherited motor neuron disease caused by homozygous deletions or mutations in the survival of the motor neuron 1 gene (SMN1) on chromosome 5 encoding the SMN protein." (PMID 35140677, 2021). "5q-associated spinal muscular atrophy (SMA) is a rare lower motor neuron disease caused by mutations in the survival motor neuron 1 (SMN1) gene resulting in deficient biosynthesis of SMN protein, death of lower motor neurons, and consequently progressive muscle wasting." (PMID 34321067, 2021). "Spinal muscular atrophy (SMA) is a rare neuromuscular disease involving anterior horn cells degeneration of lower motor neurons in the spinal cord caused by the loss of function mutations in the survival motor neuron 1 (SMN1) gene." (PMID 33995241, 2021). "Spinal muscular atrophy (SMA) is a neuromuscular disease characterized by the degeneration of motor neurons in the anterior horn of the spinal cord caused by deletions or mutations of the survival motor neuron 1 (SMN1) gene." (PMID 33962637, 2021). "SMN1 deficiency or dysfunction in motor neuron-like cells is associated with loss of growth cones, structural defects in axons that impair pathfinding and innervating abilities of these neurons, and contributes to Spinal Muscular Atrophy (SMA) pathogenesis." (PMID 32850779, 2020).
spinal muscular atrophy (continued). "Spinal muscular atrophy (SMA) is a neuromuscular disorder caused by SMN1 gene deletion/mutation." (PMID 33072999, 2019). "Spinal Muscular Atrophy (SMA) is a severe neurodegenerative disease caused by mutations in SMN1 gene, which encodes a protein that functions in the biogenesis of spliceosomal snRNPs and reduced SMN function in cells has been shown to lead to widespread aberrations in splicing." (PMID 30246013, 2018). "Mutations in the SMN1 gene results in spinal muscular atrophy (SMA), a neurodegenerative disorder characterized by progressive degeneration of spinal cord anterior horn α-motor neurons and the leading genetic cause of infant mortality with an incidence of approximately 1:6000 live births." (PMID 25852739, 2015). "Besides coilin, other proteins enriched in the CB include the survival of motor neuron protein (SMN; also known as SMN1), which is mutated in most cases of the neurodegenerative disease spinal muscular atrophy, and WRAP53, which plays a role in the telomerase holoenzyme assembly." (PMID 40342165, 2025). "Spinal Muscular Atrophy (SMA) is caused by mutations and deletions within the survival motor neuron 1 (SMN1) gene causing a motor neuron disease with childhood onset." (PMID 39810393, 2025). "Spinal muscular atrophy (SMA) is an autosomal recessive disorder caused by the deletion or/and mutation in the survival motor neuron 1 (SMN1) gene on chromosome 5." (PMID 37189623, 2023). "The deficiency or loss of function of SMN resulting from the homozygous mutation of SMN1 causes spinal muscular atrophy (SMA), the most common form of motor neuron disease in children, characterized by a severe and progressive neuromuscular pathology." (PMID 36291733, 2022). "Hereditary proximal spinal muscular atrophy (SMA) is caused by survival motor neuron (SMN) protein deficiency due to homozygous loss of function of the SMN1 gene." (PMID 32681555, 2020). "Indeed, virus-mediated gene therapies have now been approved by the FDA in the US for RPE65-associated retinal dystrophy (voretigene neparvovec marketed as Luxturna) and SMN1-linked spinal muscular atrophy (SMA; onasemnogene abeparvovec marketed as Zolgenmsa), as well as non-neuronal conditions." (PMID 32765219, 2020). "Spinal muscular atrophy (SMA), a leading genetic cause of infant death, is caused by the loss of survival motor neuron 1 (SMN1) gene." (PMID 30327977, 2019). "Spinal muscular atrophy (SMA) is genetic and progressive, caused by largebi-allelic deletions in the SMN1 gene, or the association of a large deletionand a null variant." (PMID 31844498, 2019). "The survival motor neuron (SMN) protein was first highlighted as a protein of interest when mutations in its coding gene, SMN1, were linked to the neuromuscular disease spinal muscular atrophy (SMA), a leading genetic cause of infant mortality." (PMID 29872871, 2018). "Proximal spinal muscular atrophy (SMA) is an early onset, autosomal recessive motor neuron disease caused by loss of or mutation in SMN1 (survival motor neuron 1)." (PMID 25191843, 2014). "Spinal muscular atrophy (SMA) is a common, autosomal recessive neuromuscular disease caused by mutations in the Survival of Motor Neurons 1 (SMN1) gene and thus loss of protein from the gene." (PMID 23029491, 2012). "Spinal Muscular Atrophy (SMA) is a monogenic, recessively inherited neuromuscular disorder caused by loss-of-function mutation of the Survival Motor Neuron 1 (SMN1) gene." (PMID 22558154, 2012). "Using CRISPR-QKD, we achieve effective knockdown of smn1 and simultaneous knockdown of tardbp and tardbpl, modeling spinal muscular atrophy and amyotrophic lateral sclerosis, respectively." (PMID 41671402, 2026). "This study introduces a much-needed tool for assessing SMN1 pathogenicity in spinal muscular atrophy (SMA) using the zebrafish model." (PMID 41398093, 2026).